RN7SL736P (RNA, 7SL, cytoplasmic 736, pseudogene)
Gene: Miscellaneous RNA gene on chromosome 15 (90,293,939 to 90,294,207, forward strand). Ensembl gene ENSG00000275803.
Homologues: Orthologues: chimpanzee Metazoa_SRP (83% identical), pig Metazoa_SRP (57% identical). Paralogues in human: RN7SL417P (91% identical), RN7SL214P (86% identical), RN7SL536P (85% identical), Metazoa_SRP (85% identical), RN7SL106P (85% identical), RN7SL238P (85% identical), RN7SL545P (85% identical), RN7SL759P (85% identical), RN7SL196P (82% identical), RN7SL286P (82% identical), RN7SL539P (82% identical), RN7SL796P (82% identical), and 707 more.